LDHA (lactate dehydrogenase A)
Diseases named in the same sentence as LDHA in open-access papers (continued):
Sharing a sentence is not in itself a finding about the gene and the disease.
tumor (continued). "Furthermore, animal studies demonstrated that glabridin intervention significantly slowed tumor tissue growth in mice, resulting in up-regulation of cellular Bax expression and down-regulation of B-cell lymphoma-2 (Bcl-2), HK-2, and LDHA expression in tumor tissues." (PMID 39723390, 2024). "However, EMφ EVs treatment rescued the impaired tumor growth in LDHA-depleted CT2A tumors." (PMID 38443336, 2024). "In addition, the increase in PD-L1 expression and decrease in the phosphorylation of LDHA suggest that, if similar changes occur in vivo, sunitinib resistance may affect the ccRCC tumor microenvironment by becoming more immunosuppressive and less glycolytic." (PMID 38263737, 2024). "Overall, LDHA knockdown may depress tumor growth by blocking the activation of the ERK pathway." (PMID 38627278, 2024). "In addition, LDHA promotes the proliferation of tumor cells by increasing lactic acid production." (PMID 38709280, 2024). "We demonstrated that EGFRHIGH tumor subcluster was distinctly elevated in the pembrolizumab-treated group and exhibited significantly higher level of lactate producing biomarkers including LDHA and SLC16A3 compared to the combination group in both HNSCC and LUSC PDX." (PMID 38916448, 2024). "Notably, the serum level of lactate dehydrogenase A (LDHA) was decreased after tumor removal." (PMID 37158852, 2023). "Blindly inhibiting LDHA activity to block lactate production in tumor cells may produce some unmanageable side effects, for example, pyruvate accumulation can drive ECM remodeling by inducing collagen hydroxylation, thus promoting metastatic growth in breast cancer." (PMID 37965331, 2023). "Thus, combined with the expression and prognosis value of LDHA in KICH, we inferred that the downregulation of LDHA might inhibit the anti-tumor immune response and promote the initiation of KICH." (PMID 37925501, 2023). "tRFTyr could promote lactate accumulation and tumour progression in LSCC by binding to LDHA." (PMID 37365531, 2023). "The regulatory effect of LDHA on immune escape by infiltrating T cells is mainly dependent on the excessive lactate secretion from tumor cells to the TME, which might reach levels of up to 10–40 mM over 10 times greater than physiological lactate concentrations." (PMID 36518315, 2022). "Notably, LDHA was found to be expressed mainly in the central hypoxic area of the tumor, colocalized with carbonic anhydrase IX (CAIX or CA9), and some cells invading the corpus callosum (CC), while LDHB was prevalently expressed in peripheral tumor areas and cells invading the CC." (PMID 36278433, 2022). "Furthermore, LINC01128 promoted tumor growth and regulated LDHA protein expression in vivo." (PMID 35193567, 2022). "Thus, we investigated the role of LINC01128 in promoting tumor growth mediating by LDHA." (PMID 35193567, 2022). "Additionally, LDHA functions as a biomarker for tumor diagnosis and prognosis." (PMID 36518315, 2022). "LDHA could catalyze pyruvate to lactate in tumor cells through aerobic glycolysis, knockdown LDHA in tumor cells neutralized TIME acidity, and promoted tumor infiltration by CD8+ T cells and NK cells while decreasing the number of immunosuppressive immune cells." (PMID 36072431, 2022). "Moreover, genetic silencing of LDHA suppresses tumor growth and induces apoptosis of tumor cells." (PMID 35525866, 2022). "Similarly, LDHA expression levels and stage of the tumor are positively correlated." (PMID 35783254, 2022). "However, LDHA mediates the production of lactate, which is released by the monocarboxylate transporters (MCTs), exacerbating environmental acidification and promoting environmental support for tumor metastasis." (PMID 35535311, 2022). "Notably, the glycolic inhibitors 2-DG and 3-BP or depletion of LDHA, which catalyzed the final step of glycolysis, could partly abrogate cancer cell proliferation and tumor growth." (PMID 34132347, 2021).
tumor (continued). "Furthermore, GO analysis revealed that LDHA expression was also correlated with the immune system process to a certain extent, suggesting that LDHA, as a novel target, has great prospect in the field of tumor immunotherapy." (PMID 34307169, 2021). "Moreover, LDHA activity can be further enhanced by post-translational modifications, such as the phosphorylation of tyrosine-10, which has been shown to contribute to tumor metastasis by altering cell metabolism." (PMID 33153193, 2020). "Lactate‐driven DC dysfunction was first described in monocyte‐derived DC differentiated in the context of tumor spheroids, where tumor suppression of IL‐12 secretion by DC could be reversed by blocking lactic acid production with a lactate dehydrogenase A (LDHA) inhibitor." (PMID 32508018, 2020). "Indeed, silencing/genetic disruption of LDHA inhibited tumor growth in vitro and in vivo." (PMID 32947951, 2020). "Thus, it appears that the impact of LDHA inhibition on anti-tumor and anti-tubercular immunity may have some similarities." (PMID 32034005, 2020). "In our analysis, LDHA was identified in six secretome studies and only two from the proteome, suggesting that this enzyme may be secreted to perform its functions in tissues distant from the primary tumor focus, exacerbating the tumor progression." (PMID 32197468, 2020). "Moreover, overexpression of LDHA was shown to antagonize the tumor‐suppressing effects of miR‐33b." (PMID 30368888, 2019). "Furthermore, we investigated whether MA could affect activity and expression of LDHA in the tumor tissues of mice inoculated with LLC cells." (PMID 31324019, 2019). "Therefore, LDHA is a key mediator of Warburg effect of tumor cells." (PMID 31523182, 2019). "Additionally, reducing the production of lactate via knockdown of lactate dehydrogenase A (LDHA) in tumor cells was also demonstrated that could neutralize of the tumor acidity and enhance the anti-PD-L1-mediated immunotherapy." (PMID 31754379, 2019). "Therefore, the inhibition of LDHA activity may provide an opportunity for anti-cancer agents to interfere with tumor growth and invasiveness." (PMID 30886157, 2019). "Moreover, the silencing of LDHA inhibited tumor growth in vivo." (PMID 31921691, 2019). "The enzyme LDHA has been shown to be essential for angiogenesis in microvascular ECs, and studies in a variety of human cancer types have documented an association between tumor lactate levels and negative clinical outcomes." (PMID 31471554, 2019). "Moreover, aerobic glycolysis remodels the ECM and facilitates EMT-inducing transcription factor expression by increasing the lactate content surrounding cancer cells and reducing the pH of the tumor microenvironment; these factors indicate that LDHA induces EMT and promotes cancer cell metastasis." (PMID 31921691, 2019). "Thus, a double knockdown of LDHA/B should be performed to validate in details how these enzymes (all isoforms) control pivotal events in the metabolism and production of lactic acid in tumor cells." (PMID 31035592, 2019). "As the tumor 13C pyruvate-to-lactate conversion was measured over a much larger tumor volume compared to the LDHA expression that was assayed from a very small sample of the harvested tumors; it is possible that any potential intra-tumoral heterogeneity might explain the discrepancy." (PMID 30189677, 2018). "These preliminary metabolite results are promising and suggest that levels of metabolites along with potential tumour biomarkers such as LDHA could contribute to a panel of markers that could provide insight into tumour biology, associated with corresponding biopotential profiles." (PMID 30279418, 2018). "Diverse studies have shown that LDHA could regulate tumor angiogenesis." (PMID 30403008, 2018). "Thus, increased expression of PKM and LDHA in CACs might be resulting in the tumor cell survival by preventing the entry of glycolytic pathway into feedback inhibition loop by the end product of the pathway." (PMID 29568375, 2018).
tumor (continued). "However, previous studies in other cell lines that had also not achieved a 100% knockdown of LDHA found it caused a significant reduction in tumour cell migration, growth and maintenance, similar to the results we saw with oxamate." (PMID 29601482, 2018). "Moreover, LDHA was positively correlated with JMJD2A expression in tumor specimens." (PMID 28693517, 2017). "There are several other possible mechanisms in which LDHA may promote tumor growth." (PMID 26269128, 2016). "In addition, c-Myc has also been shown to regulate energy metabolism by regulating LDHA in tumor." (PMID 25887760, 2015). "Moreover, LDHA plays an important role in the aerobic-anaerobic switch and may drive anaerobic tumor metabolism." (PMID 24879114, 2014). "Notably, the tumor cells near the necrotic tissues markedly expressed LDHA." (PMID 23456655, 2013). "Thus, increasing PKM2 activation could provide yet another mechanism for LDHA inhibitors to reduce tumor growth." (PMID 24280423, 2013). "Dysregulated LDH expression, particularly upregulation of LDHA and downregulation of LDHB, promotes tumor progression." (PMID 40818043, 2026). "Ultimately, we carefully chose LDHA and KRT7 to explore their oncogene role in LUAD, given that they were significantly upregulated in tumor tissues in both mRNA and protein levels, while they were risky genes based on survival analysis." (PMID 41488744, 2026). "Immunohistochemical analysis of these tumours confirmed that the combination therapy significantly reduced the expression of both AKR1B10 and LDHA." (PMID 41454479, 2026). "Researchers have found that LDHA maintains NAD+ regeneration for glycolytic flux, with siRNA‐mediated knockdown suppressing tumor cell proliferation in vitro." (PMID 41488744, 2026). "When combined with the LDHA inhibitor FX11, it induced synergistic anti-tumor effects in organoid and patient-derived xenograft models, thereby significantly inhibiting tumor progression and prolonging survival." (PMID 41736673, 2026). "As CRC cells progressed, as indicated by KRAS expression, the expression of tumor acidosis markers (LAMP2, GLUT1, and LDHA), as well as dysadherin, also increased." (PMID 41535258, 2026). "Spatial transcriptomics data from HCCDB further demonstrated that LDHA expression levels were significantly higher than LDHB within HCC cells, while LDHB was predominantly expressed in immune cells of the tumour microenvironment." (PMID 41454479, 2026). "c‐myc promotes the production and export of lactate by increasing the gene expression of LDHA and the lactate transporter MCT1, helping to maintain the acidic microenvironment of tumour cells and thus promoting tumour invasion and metastasis." (PMID 39778006, 2025). "Low GLUT1/MCT4 in tumor cells, high MCT4 in stromal cells, and high expression of LDHA play a key role in the reverse Warburg effect, which is of great significance for the reversal of TNBC metastasis." (PMID 40723842, 2025). "Reduced LDHA activity not only impairs glycolytic energy supply but also decreases extracellular LA export through MCT4, alleviating tumor microenvironment (TME) acidosis." (PMID 40944197, 2025). "MYC, a key regulator of oncogenic metabolism, promotes glycolysis (via LDHA, PFK1), glutamine metabolism (via GLS1), and mitochondrial biogenesis to fuel rapid tumor proliferation." (PMID 40814172, 2025). "Here, we demonstrate that AHCY is overexpressed in ESCC, enhances LDHA stability and glycolytic activity, and its inhibition suppresses ESCC proliferation and tumor growth." (PMID 41163796, 2025). "Inhibiting LDHA reduces lactate levels, alleviates TME acidification, and reprograms TAMs toward a pro-inflammatory M1-like phenotype, thereby enhancing anti-tumor immunity." (PMID 40433363, 2025). "In HeLa cells, treatment with 2-deoxyglucose or thapsigargin triggers ER stress, which upregulates lactate dehydrogenase A (LDHA) and LDHB subunits, facilitating cellular adaptation to aerobic glycolysis and enhancing tumor proliferation." (PMID 41209558, 2025).
tumor (continued). "EV-Driven Metabolic Reprogramming: Emerging evidence suggests that CAF-EVs transfer lactate dehydrogenase A (LDHA) and glutamine synthetase to tumor cells, fostering an acidic, nutrient-depleted microenvironment that impairs T-cell glycolysis and cytotoxicity." (PMID 40475777, 2025). "The results showed that LDHA was downregulated and SLC16A1 was upregulated in LGG tumor tissues compared to normal tissues in TCGA dataset." (PMID 40782248, 2025). "Glycolysis genes HK1, GAPDH, ENO1, LDHA, and PKM, and cell cycle genes (except CCND2) were among the most tumor-specific genes." (PMID 39774001, 2025). "To investigate the cooperative role of NDRG1 and LDHA in glycolysis, we first examined how NDRG1 affects glucose uptake and mitochondrial function in tumor cells." (PMID 40539245, 2025). "Although most research focuses on LDHA, recent data suggest that LDHB silencing also reduces lactate flux and tumor cell viability, indicating its complementary role in targeting lactate-driven resistance." (PMID 40843350, 2025). "Our study demonstrated that reducing SLC7A5 expression significantly decreased HK2, LDHA, Glut1, and PDK1 levels in HGC27R cells, MKN45R cells, and tumor tissues." (PMID 40133832, 2025). "Lately, Wang et.al found that ALDH1A1 enhances the transcriptional regulation of LDHA by ZBTB7B, leading to increased lactate production and reduced anti-tumor immune cell infiltration." (PMID 39897050, 2025). "Simultaneously, treatment with PP2 significantly reduced nuclear PKM2 levels, suppressing the transcription of its downstream target genes (such as GLUT1, LDHA, and MYC) and markedly weakening tumor cells’ glycolytic capacity and proliferative ability." (PMID 41216192, 2025). "In lymphoma models, curcumin downregulates LDHA activity and expression by targeting the c-Myc and HIF-1α signaling pathways, thereby reducing glycolysis and inhibiting tumor progression." (PMID 41515171, 2025). "The protein level of LDHA was relatively low and SLC16A1 was higher in tumor tissues than in controls." (PMID 40782248, 2025). "The expression levels of LDHA and SLC16A1 in GSE15824 and GSE16011 of all tumor samples (grades I–IV) were also extracted." (PMID 40782248, 2025). "HULC has been found to bind directly to and increase the phosphorylation of key glycolytic enzymes LDHA and PKM2, thereby promoting glycolysis and enhancing tumor progression." (PMID 40909946, 2025). "Building on the rationale that key glycolytic enzymes, such as HK2, LDHA, and PKM2, are central drivers of both tumor metabolism and the radioresistant TME, the following section focuses on therapeutic strategies directly targeting these molecules." (PMID 41441035, 2025). "Inhibition of the glycolytic key enzyme LDHA or use of LDH inhibitors (such as sodium oxalate) can enhance CD8+ T cell killing ability, reverse tumor immune escape, and produce a synergistic effect with anti-PD-1 therapy." (PMID 41181157, 2025). "Strikingly, only three genes—ITGB4, LDHA, and TIMP1—demonstrated significantly higher expression in tumor epithelial cells compared to their normal counterparts." (PMID 41187171, 2025). "We observed diverse LDHA expression in LGG, possibly due to the heterogeneity of the tumor samples and differences in tumor purity‌." (PMID 40782248, 2025). "Subcutaneous injection of these LDHA‐overexpressing SW480 and Caco‐2 cells into nude mice significantly promoted tumour growth, as evidenced by increased tumour size and volume, and elevated intratumoural lactate levels." (PMID 41399129, 2025). "PITX2 and KCNK1 as well as ZDHHC9-mediated palmitoylation up-regulate LDHA expression, promote lactate production, then lactylate H3K18 and down-regulate HDAC1/2 to inhibit H3/H4 acetylation, ultimately inhibiting tumor cell proliferation." (PMID 40165895, 2025).
tumor (continued). "Some studies have shown that ALDH3A1 promotes glycolysis and lactate accumulation through activation of the LDHA pathway; inhibition of ALDH3A1 reduces lactate levels and inhibits tumor cell proliferation." (PMID 41228459, 2025). "LDHA enhances glycolysis and lactate production in pancreatic ductal adenocarcinoma (PDAC) cells, whereas CAFs utilize tumor-derived lactate via MCT1 as an energy source to sustain their proliferation." (PMID 41152975, 2025). "Strikingly, only three genes - ITGB4, LDHA, and TIMP1 – showed significantly elevated expression in tumor epithelial cells compared to their normal counterparts (P < 0.01)." (PMID 41187171, 2025). "Inhibiting LDHA reduces lactate buildup, restoring a high-glucose, low-lactate microenvironment that promotes CD8+ T-cell activation and strengthens anti-tumor immunity." (PMID 41050070, 2025). "Studies have demonstrated that HULC can directly bind to and increase the phosphorylation of both LDHA and PKM2, thereby enhancing glycolysis in HCC cell lines and facilitating tumor progression." (PMID 40909946, 2025). "Lactate treatment inhibited the antitumor immunity of CD8+ T cells, whereas interruption of glycolysis via LDHA knockdown or treatment with sodium oxamate augmented the cytotoxicity of CD8+ T cells, effectively counteracting tumor immune evasion." (PMID 39990209, 2025). "Methyltransferase-like 3 (METTL3) regulates tumor metabolic reprogramming by controlling the expression of glucose transporters (GLUTs), lactate dehydrogenase (LDHA), and enolase 1 (ENO1) in tumor cells." (PMID 40046061, 2025). "Dysregulation of LDH levels, characterized by the overexpression of LDHA and the downregulation of LDHB, often promotes tumor proliferation." (PMID 40755753, 2025). "Greater expression of glucose transporter 1 and lactate dehydrogenase A (LDH), together with increased protein content and activity of LDH in tumours, suggested a higher glycolytic capability." (PMID 40045444, 2025). "One recent study pointed out that LDHA upregulated C-C motif chemokine ligand 2 (CCL2) and CCL7 through the ERK-YAP-STAT3 signaling axis to recruit macrophages into the tumor microenvironment." (PMID 40093910, 2025). "Investigators from the University of South China and Central South University reported that TAB182 regulates lactate dehydrogenase A (LDHA) transcription, modulating glycolysis and lactate production and thereby contributing to tumor radioresistance." (PMID 41441035, 2025). "Meanwhile, lactate reinforces tumor glycolysis through HIF-1α- and c-Myc-dependent upregulation of LDHA and MCT4, establishing a positive feedback loop that sustains energy production in PC cells and contributes to immune evasion." (PMID 41458606, 2025). "This resulted in an increased cytosolic NAD+/NADH ratio, which enhanced the phosphorylation of pyruvate kinase M2 (PKM2) and lactate dehydrogenase A (LDHA), thus promoting TNBC tumor progression." (PMID 40611146, 2025). "Previous studies have indicated that CHD1 supports tumor growth by modulating metabolic genes such as HK2 and LDHA, with its inhibition suppressing proliferation and inducing apoptosis, particularly in PTEN-deficient models." (PMID 41249788, 2025). "The data indicate that using the LDHA inhibitor stridently or knocking out LDHA effectively inhibited NBS1 K388 lactylation, thereby improving chemotherapy resistance in tumor cells." (PMID 41373440, 2025). "HIF-1α plays a pivotal role in tumor metabolism by promoting glycolysis through the upregulation of GLUT1, HK2, and LDHA." (PMID 41281744, 2025). "Together, these results indicated that LDHA expression was regulated by FOXO3a/miR4259 signaling and positively correlated with gemcitabine tolerance in PDAC tumours." (PMID 39930542, 2025). "LDHA inhibitors, such as GSK2837808A or NCI-006, reduce lactate production and tumor growth, but their impact on immune cell function requires further validation." (PMID 40734168, 2025).